KCNH1 (potassium voltage-gated channel subfamily H member 1)
Description:
Pore-forming (alpha) subunit of a voltage-gated delayed rectifier potassium channel that mediates outward-rectifying potassium currents which, on depolarization, reaches a steady-state level and do not inactivate. The activation kinetics depend on the prepulse potential and external divalent cation concentration. With negative prepulses, the current activation is delayed and slowed down several fold, whereas more positive prepulses speed up activation. The time course of activation is biphasic with a fast and a slowly activating current component. Activates at more positive membrane potentials and exhibit a steeper activation curve. Channel properties are modulated by subunit assembly. Mediates IK(NI) current in myoblasts. Involved in the regulation of cell proliferation and differentiation, in particular adipogenic and osteogenic differentiation in bone marrow-derived mesenchymal stem cells (MSCs).
Synonyms: h-eag; hEAG1; EAG; EAG1; Kv10.1; hEAG; K(V)10.1; TMBTS; ZLS1
Tractability: Small molecule: an approved drug acts on it; a high-quality ligand is known; it belongs to a druggable protein family. Antibody: UniProt places it where antibodies can reach, with high confidence; its Gene Ontology location is reachable by antibodies, with high confidence; UniProt predicts a signal peptide or a membrane-spanning region. PROTAC: a small molecule that binds it is known.
Target class: Potassium channels; Ion channel; Voltage-gated ion channel; Voltage-gated potassium channel
Gene: Protein-coding gene on chromosome 1 (210,676,823 to 211,134,183, reverse strand). Ensembl gene ENSG00000143473.
Subcellular location: Cell membrane; Nucleus inner membrane; Cell projection, dendrite; Cell projection, axon; Presynaptic cell membrane; Perikaryon; Postsynaptic density membrane; Early endosome membrane
Subcellular location (Human Protein Atlas): Vesicles
Pathways (Reactome):
Neuronal System: Voltage gated Potassium channels
Gene Ontology:
Molecular function: delayed rectifier potassium channel activity; phosphatidylinositol bisphosphate binding; protein binding; cyclic nucleotide binding; monoatomic ion channel activity; voltage-gated potassium channel activity
Biological process: cellular response to calcium ion; potassium ion transmembrane transport; potassium ion transport; regulation of cell population proliferation; myoblast fusion; regulation of membrane potential; regulation of presynaptic cytosolic calcium ion concentration; monoatomic ion transport; transmembrane transport
Cellular component: early endosome membrane; plasma membrane; voltage-gated potassium channel complex; perikaryon; postsynaptic density membrane; presynaptic membrane; axon; dendrite; membrane; nuclear inner membrane
Genetic constraint (gnomAD): Loss-of-function variants: 27 observed, 70.76 expected, observed/expected ratio (o/e) 0.38, 90% interval 0.28 to 0.53. The upper end of that interval is the gene's LOEUF score, 0.53, which puts it in group 2 of 6, group 1 being the genes least tolerant of losing a copy. Missense variants: 784 observed, 1,282 expected, observed/expected ratio (o/e) 0.61, 90% interval 0.58 to 0.65. Synonymous variants: 447 observed, 499.33 expected, observed/expected ratio (o/e) 0.9, 90% interval 0.83 to 0.97.
Gene-disease validity (ClinGen):
ClinGen rates the evidence that KCNH1 causes each of these diseases.
KCNH1 associated disorder (autosomal dominant): Definitive. Any neurodevelopmental disorder in which the cause of the disease is a mutation in the KCNH1 gene.
Homologues: Orthologues: chimpanzee KCNH1 (100% identical), guinea pig KCNH1 (98% identical), rat Kcnh1 (98% identical), rabbit KCNH1 (97% identical), macaque KCNH1 (97% identical), pig KCNH1 (96% identical), dog KCNH1 (95% identical), mouse Kcnh1 (94% identical), tropical clawed frog kcnh1 (88% identical), zebrafish kcnh1a (80% identical), zebrafish kcnh1b (79% identical), Drosophila melanogaster eag (53% identical), and 2 more. Paralogues in human: KCNH5 (73% identical), KCNH2 (34% identical), KCNH7 (33% identical), KCNH8 (32% identical), KCNH6 (31% identical), KCNH3 (31% identical), KCNH4 (31% identical), HCN4 (17% identical), HCN1 (16% identical), HCN2 (16% identical), HCN3 (15% identical), CNGA2 (14% identical), and 5 more.
Diseases named in the same sentence as KCNH1 in open-access papers:
KCNH1 is named in the same sentence as 93 diseases in open-access papers, as found by Europe PMC text mining. Sharing a sentence is not in itself a finding about the gene and the disease. The quoted sentences say what the papers report.
breast cancer (17 papers, 2006 to 2025). A primary or metastatic malignant neoplasm involving the breast. "In distinct types of cancer, KCNH1 undergoes different genetic alterations, amplification being the most frequent in breast cancer." (PMID 35955591, 2022). "The amplification of the KCNH1 gene is reported in five breast cancer studies, with a variation between 6.5–30.3%." (PMID 35955591, 2022). "Interestingly, a noteworthy finding was that 4-OH-TMX can also suppress KCNH1 gene expression in breast cancer cells." (PMID 38004441, 2023). "The gene amplification in low-level (gain) and high-level (amplification) show the highest levels of mRNA KCNH1 expression, which may account for the increased expression of KCNH1 in breast cancer." (PMID 35955591, 2022). "Breast cancer samples with ER+ subtype showed significantly higher mRNA KCNH1 expression." (PMID 35955591, 2022). "Breast cancer studies included E1 (KCNMB1), E4 (KCNN3), E9 (KCNH1, KCNK15), E15 (KCNT2), E22 (KCNK5, KCNK15), E33 (KCNQ1-OT1), E38 (KCNMA1), E48 (KCNJ9), and E63 (KCNK12)." (PMID 40867621, 2025).
cervical carcinoma (15 papers, 2006 to 2025). A carcinoma arising from either the exocervical squamous epithelium or the endocervical glandular epithelium. "KCNH1 overexpression has been implicated in cancer cell proliferation and tumor growth in cervical carcinoma and other soft tissue sarcomas." (PMID 38895237, 2024). "Remarkably, the effect of AM upon E6-, E7-HPV16, and KCNH1 expression in the tumor mass was similar to that observed in vitro in cultured cervical cancer cells." (PMID 36769377, 2023). "In MCF-7 and T-47D cell lines, we observed a significant reduction in KCNH1 gene expression levels with AM, similar to findings reported in cervical cancer." (PMID 38004441, 2023). "Our previous studies have demonstrated that AM decreased KCNH1 gene expression in cervical cancer cells, both in vitro and in vivo." (PMID 38004441, 2023). "Based on the in vitro effects of AM on the E6/E7 HPV oncogenes and KCNH1 gene expression, we evaluated these effects on the tumor tissue from xenografted SiHa cervical cancer cells." (PMID 36769377, 2023). "In this study, we report for the first time that AM inhibited KCNH1 gene expression both in vitro and in vivo, which adds to the described potential mechanism by which this xanthone inhibits cervical cancer cell proliferation." (PMID 36769377, 2023). "In cervical cancer, KCNH1 is considered a potential tumor marker and therapeutic target." (PMID 36769377, 2023). "High KCNH1 expression has been demonstrated in several biological models of lung and HPV+ cervical cancers." (PMID 37408210, 2023). "The phytochemical AM induces cell cycle arrest, cell death, and tumor growth inhibition in cervical cancer by downregulating HPV E6/E7 and KCNH1 oncogenes gene expression, highlighting its potential as an effective antitumoral agent for this neoplasia." (PMID 36769377, 2023). "Eag1 (ether a′-go-go-1, KCNH1, Kv10.1) is a specific form of voltage-gated potassium channel that shows restricted expression in healthy tissues, but its presence has been detected in several types of tumors, including cervical cancers." (PMID 39337406, 2024).
epilepsy (13 papers, 2015 to 2026). A brain disorder characterized by episodes of abnormally increased neuronal discharge resulting in transient episodes of sensory or motor neurological dysfunction, or psychic dysfunction. "We analyzed the largest cohort of 51 patients with KCNH1 variants to date and found that epilepsy/seizures were present in 82% individuals suggesting a direct role of KCNH1 in epileptogenesis." (PMID 36285361, 2023). "Variants in the KCNH1 cause a spectrum of epileptic disorders ranging from a benign form of genetic isolated epilepsy/FS to intractable form of epileptic encephalopathy." (PMID 36285361, 2023). "Mutations in the KCNH1 cause a spectrum of epileptic disorders ranging from a benign form of genetic isolated epilepsy/febrile seizure to intractable form of epileptic encephalopathy." (PMID 36285361, 2023). "Two novel KCNH1 variants were identified in three cases, including two patients with FS with inherited variant (p.Ile113Thr) and one boy with epilepsy with de novo variant (p.Arg357Trp)." (PMID 36285361, 2023). "We also analyzed all previously reported patients with KCNH1 variant, focusing on the correlations between epilepsy and molecular sub‐regional locations." (PMID 36285361, 2023). "The phenotypic spectrum of KCNH1 pathogenic mutations includes a wide range of symptoms, from syndromic neurodevelopmental disorders to epilepsy." (PMID 35639255, 2022). "In this report, we present patients harboring novel missense mutations in the KCNH1 gene suffering from epilepsy, but otherwise presenting distinct clinical features, broadening the phenotypic spectrum of KCNH1 mutations." (PMID 33494179, 2021). "The 2 SNPs discarded by the Midrange Filter are located within genes associated with phenotypes unrelated to the mental health diagnoses of the PsyCourse participants: KCNH1 is associated with epilepsy and severe and rare development disorders, while TMEM200A is associated with gastric cancer." (PMID 40053832, 2025). "We found two novel missense variants of KCNH1 in three individuals with isolated FS/epilepsy." (PMID 36285361, 2023). "In conclusion, we found two novel missense variants of KCNH1 in three individuals with FS/epilepsy." (PMID 36285361, 2023). "Here, we reported three cases harboring novel variants in the KCNH1 gene suffering from epilepsy/febrile seizure (FS) and refractory status epilepticus (SE), but otherwise presenting distinct clinical features of TBS or ZLS, broadening the phenotypic spectrum of KCNH1." (PMID 36285361, 2023). "To date, 45 patients with 24 KCNH1 mutations have been reported with a phenotype characterized by a remarkable clinical heterogeneity, from mild to severe developmental delay and/or ID and epilepsy." (PMID 35639255, 2022). "Seizures and/or epilepsy is a typical hallmark of the KCNH1 disorder (89%)." (PMID 33594261, 2021). "More recently, pathogenic KCNH1 mutations have been identified in uncharacterized patients with intellectual disability, epilepsy and variable skeletal abnormalities, which could be ascribed neither to a ZLS nor to a TMBTS phenotype." (PMID 33494179, 2021). "They pointed out that patients who have multiple manifestations of seizure types, severity, and response to treatments with a low level of mosaic/somatic variant or a weaker effect on KCNH1 function of the inherited variant may lead to isolated epilepsy phenotype." (PMID 39434833, 2024). "This study aimed to expand the phenotypic spectrum of KCNH1 and explore the correlations between epilepsy and molecular sub‐regional locations." (PMID 36285361, 2023). "All those phenotypes are characterized by neurological manifestations, including ID and epilepsy, suggesting an important role for KCNH1 in human neurodevelopment." (PMID 35639255, 2022). "Epilepsy is a prominent phenotypic feature in most individuals with KCNH1-related syndromes." (PMID 39434833, 2024).
epilepsy (continued). "Present study provided a clinical description of three individuals with two novel missense variants of KCNH1 with FS/epilepsy and refractory SE without features of TBS/ZLS." (PMID 36285361, 2023). "KCNH1 missense variants have been associated with syndromic neurodevelopmental disorders, including Zimmermann-Laband syndrome 1 (ZLS1, MIM #135500), Temple-Baraitser syndrome (TMBTS, MIM #611816), and, recently, with milder phenotypes as epilepsy." (PMID 35639255, 2022).
Intellectual disability (8 papers, 2015 to 2026). "Gain-of-function (GoF) mutations in KCNH1 (Kv10.1, hEAG1) and KCNH5 (Kv10.2, hEAG2) give rise to developmental disorders, intellectual disability, and epilepsy." (PMID 41656275, 2026). "Here, we describe four patients suffering from a rather broad spectrum of epilepsy-related disorders, ranging from developmental and epileptic encephalopathy with intellectual disability (DEE) to genetic generalized epilepsy (GGE), which all harbor novel KCNH1 mutations." (PMID 33494179, 2021). "More recent studies expanded the phenotype spectrum of KCNH1-related encephalopathies to subjects with severe intellectual disability, mild extra-neurological phenotype, and lacking the distinctive features of TMBTS and ZLS1." (PMID 35639255, 2022).
Temple-Baraitser syndrome (7 papers, 2015 to 2023). Temple-Baraitser syndrome is a rare developmental anomalies syndrome characterized by severe intellectual disability and distal hypoplasia of digits, particularly of thumbs and halluces, with nail aplasia or hypoplasia. "For instance, mutations in Cav1.2 channels in Timothy syndrome, sodium leak channel mutations in Freeman-Sheldon syndrome and mutations in voltage gated potassium channel KCNH1 (Kv10.1) in Temple-Baraitser syndrome are examples of channelopathies due to mis-regulated ion channels." (PMID 33200809, 2020). "This group has also recently identified the previously unknown genetic cause of Temple-Baraitser syndrome to be due to mutations in KCNH1." (PMID 26374634, 2015).
Zimmermann-Laband syndrome (7 papers, 2017 to 2025). A rare disorder characterized by gingival fibromatosis, coarse facial appearance, and absence or hypoplasia of nails or terminal phalanges of hands and feet. "Clinical features of subjects with biallelic TBC1D2B pathogenic variants show phenotypic overlap with syndromic neurodevelopmental K+ channelopathies or Zimmermann-Laband syndrome associated with dominant KCNN3, KCNH1, and KCNK4 variants." (PMID 38374468, 2024).
osteosarcoma (6 papers, 2012 to 2024). A usually aggressive malignant bone-forming mesenchymal neoplasm, predominantly affecting adolescents and young adults. "α-Mangostin (10 μM) induced cell cycle arrest and decreased the expression of HPV16 oncogenes (E6 and E7) and potassium voltage-gated channel subfamily H member 1 (KCNH1), whose overexpression was found to be associated with osteosarcoma pathogenesis in xenografted SiHa cells." (PMID 39595559, 2024).
developmental delay (4 papers, 2021 to 2024). "There is notable overlap in the phenotypic findings of these syndromes associated with dominant KCNN3, KCNH1, and KCNK4 variants, sharing developmental delay and/or ID, coarse facial features, gingival enlargement, distal digital hypoplasia, and hypertrichosis." (PMID 33594261, 2021).
hypertrichosis (4 papers, 2021 to 2024). Excessive hair growth anywhere on the body. "Both features were consistently present in individuals with KCNK4 variant affecting function and variably present in patients with dominant KCNN3 (30% for hypertrichosis and 67% for gingival enlargement) or KCNH1 variant (19% for hypertrichosis and 79% for gingival enlargement)." (PMID 33594261, 2021). "Based on the data, the overarching phenotype associated with dominant KCNH1, KCNN3, and KCNK4 variants comprised DD and/or ID, hypotonia, coarsening facial features, gingival enlargement, and hypertrichosis." (PMID 33594261, 2021). "Similarly, all individuals with dominant KCNK4 variant (100%) had hypertrichosis, while only 3/16 (19%) and 3/6 (50%) with dominant KCNH1 and KCNN3 variant, respectively, showed hypertrichosis." (PMID 33594261, 2021).
Epileptic encephalopathy (3 papers, 2015 to 2023). A condition in which epileptiform abnormalities are believed to contribute to the progressive disturbance in cerebral function. "Variants in the KCNH1 cause a spectrum of epileptic disorders ranging from benign isolated epilepsy/FS to severe epileptic encephalopathy." (PMID 36285361, 2023).
gastric cancer (3 papers, 2022 to 2025). A primary or metastatic malignant neoplasm involving the stomach. "On the other hand, the gene for Kv10.1 (KCNH1) was found to be heavily methylated in human gastric cancer tissues." (PMID 38976181, 2024). "It will be interesting, for example, to determine the pathophysiological consequence(s) of the KCNH1 methylation in human gastric cancer which is known to express Nav1.7 at least at mRNA level." (PMID 38976181, 2024). "A study on DNA methylation in human gastric carcinoma found hypermethylation in the CpG island of 15 genes, KCNH1 was among them, suggesting a significant role in gastric cancer development." (PMID 35955591, 2022). "KCNH1 showed a three-times methylation-positive rate in gastric carcinoma samples than in noncancerous control samples." (PMID 35955591, 2022).
glioma (3 papers, 2012 to 2023). A benign or malignant brain and spinal cord tumor that arises from glial cells (astrocytes, oligodendrocytes, ependymal cells). "Voltage-gated K+ channels, human ether-a-go-go-related channel (hERG, also known as Kv11.1 and encoded by the gene KCNH2), and hEAG (human ether a-go-go, Kv10.1, KCNH1) are expressed in gliomas where they have been shown to control proliferation and apoptosis." (PMID 36768856, 2023).
melanoma (3 papers, 2006 to 2016). A malignant, usually aggressive tumor composed of atypical, neoplastic melanocytes. "Previous work investigating the oncogenic potential of a closely related EAG potassium channel (EAG1/KCNH1; ∼70% homologous to KCNH5) detected expression in several somatic cancer cell lines (including melanoma), normal adult brain and placenta, but not in other normal somatic cells." (PMID 24759919, 2014).
neuroblastoma (3 papers, 2011 to 2024). Neuroblastoma (NB) is the most common solid, extracranial childhood tumor. "Protein abundance of KCNH1 was comparable to targets under development in neuroblastoma including NCAM1, L1CAM and CD276, and higher than other known immunotherapeutic targets such as ALK and GPC2." (PMID 38895237, 2024).
developmental and epileptic encephalopathy (2 papers, 2021 to 2025). An epilepsy associated with developmental impairment that may be due to either the underlying etiology or the superimposed epileptic activity, or both. "Cerebral folate deficiency was demonstrated in nine patients (one with KCNH1-related developmental and epileptic encephalopathy, one with DHPR deficiency, one with Glut1 deficiency, one with a PRRT2 pathogenic variant, and five with no established etiological diagnosis)." (PMID 41300631, 2025).
liposarcoma (2 papers, 2006 to 2022). A usually painless malignant tumor that arises from adipose tissue. "Eag1 (KCNH1), a potassium channel, was reported to be involved in the proliferation and cell cycle of liposarcoma cells." (PMID 35326596, 2022).
Parkinson disease (2 papers, 2017 to 2019). A progressive degenerative disorder of the central nervous system characterized by loss of dopamine producing neurons in the substantia nigra and the presence of Lewy bodies in the substantia nigra and locus coeruleus. "For example, the Parkinson’s disease (PD) network in KEGG does not include many significant entities which play a crucial role in PD, such as the methylation of KCNH1, the rs393152 variant in CRHR1, and S87 SNCA phosphorylation." (PMID 31604427, 2019).
asthma (1 paper, 2021). "Kcnh1, in particular, is of interest, as it has been linked to asthma-related outcomes." (PMID 33868365, 2021).
cardiac arrhythmia (1 paper, 2012). Any disturbances of the normal rhythmic beating of the heart or MYOCARDIAL CONTRACTION. "In the case of KCNH1, which encodes the protein hEAG1, the ADR-S workflow provides evidence indicating that mutations in an animal model showed an association with prolonged QT interval and cardiac arrhythmia." (PMID 22496632, 2012).